KMT2D (lysine methyltransferase 2D)
Diseases named in the same sentence as KMT2D in open-access papers (continued):
Sharing a sentence is not in itself a finding about the gene and the disease.
cancer (continued). "We also preliminarily verified the function of cancer-associated candidate genes (CTNNB1 and KMT2D)." (PMID 33968779, 2021). "Based on exome sequencing, 40 cancer-associated genes were found to be mutated in more than one sample, with SRGAP3 and KMT2D as the most common alterations (each in four cases)." (PMID 34885165, 2021). "KMT2D was a gene of histone methyltransferase that methylates the Lys-4 position of histone H3, and there some research in other cancers, but there was still a lack of reports in ESCC." (PMID 35127817, 2021). "We found a rather narrow range of other genes (KMT2D, FBXW7, GNAS, ARID1A, NF1 and CTNNB1) harbouring mutations in 6–12% of the patients and a long tail of cancer genes with mutations in <6%." (PMID 34647903, 2021). "Studies in mouse models highlight the importance of KMT2D in regulating a wide range of biological processes, including embryonic development, cell differentiation, metabolic homeostasis, and cancer." (PMID 34336928, 2021). "Together, these findings underscored the critical role of the KMT2D gene in lymphoid malignancy and provided a potential therapeutic target for this cancer." (PMID 32164600, 2020). "The results showed that ATM, CHD4, FAT1, KMT2D, MED12, NF2, and SUFU were the most frequently mutated cancer-related genes." (PMID 33193598, 2020). "In one study on four patients, intriguingly, KMT2D, another COMPASS component, was frequently mutated in morphologically normal urothelial tissue from cancer-carrying bladders." (PMID 32326336, 2020). "Together, these results support previous findings that KMT2D is important for the propagation of established human cancer cells and further validate GE-MAQ11,20." (PMID 30131529, 2018). "It has been proposed that cancer-associated mutations in KMT2C and KMT2D exert their properties through the malfunction of KMT2C/KMT2D-dependent enhancers." (PMID 25537518, 2015). "In contrast, knockdown of KMT2D resulted in reduced cancer cell proliferation and altered adhesion in HeLa cells." (PMID 24240169, 2013). "Intriguingly, knockdowns of KMT2C and KMT2D, each in a single cell type, yielded contradictive results in term of their impact on cancer cell proliferation." (PMID 24240169, 2013). "Additional cancers that have recently been found to be driven by an aberrant KMT2D/KMT2C pathway, with frequencies ranging from 5% to 40%, include renal, prostate, bladder, gastric, hepatic and lung cancer." (PMID 24240169, 2013). "By temporally dissecting mutations, we emphasized the significance of two cancer pathways, RTK-RAS and histone modification (especially KMT2D, KDM6 A and CREBBP), in the initiation of NMIBC due to the high enrichment in early mutations and high early selection preference, respectively." (PMID 40247187, 2025). "Furthermore, CDC42BPB, CKAP4, KMT2D, and PBX2 have been shown to be strongly associated with the development of certain cancers." (PMID 40608007, 2025). "Pharmacological modulation of this phosphorylation event may offer a precision strategy to restore or fine tune KMT2D activity in cancer and developmental syndromes." (PMID 41341998, 2025).
cancer (continued). "Abnormal expression of KMT2D has been validated in various human cancers, including NSCLC." (PMID 40718439, 2025). "On the other hand, KMT2D protein expression in KMT2DLOF cell lines was significantly lower in the pan-cancer dataset and trended lower than in KMT2DWT cell lines across all nine cancer type-specific datasets for which data were available, including COAD/READ, LUSC, SCLC, STAD, and UCEC." (PMID 39578878, 2024). "The KMT2D gene has been described as mutated in IVLBCL; our sample carries a different mutation, the E1658* nonsense variant with a VAF of 9.4%, which has been described in other cancers though." (PMID 38441683, 2024). "Similarly, an analysis of the genomic landscape of MSI-H in 11,395 tumors across 30 cancer types showed that mutations in ACVR2A (73%), KMT2D (68%), KMT2B (66%), and MMR-related genes were enriched in the MSI-H group." (PMID 38281914, 2024). "KMT2D has been reported to play an anti-cancer role in ESCC." (PMID 39834937, 2024). "The analysis of KMT2D reveals that KMT2D may mainly play a role in the aging of osteoporotic cells through epigenetics and the value in pan-cancer." (PMID 39867575, 2024). "In addition to the role that KMT2D plays in developmental disorders like Kabuki syndrome, it has been found to play a dual role in various types of cancer." (PMID 38791111, 2024). "In addition, inactivation of the catalytic activities of KMT2D and p300 abolished their ability to regulate enhancer activity in different cancers." (PMID 37410700, 2023). "Genes encoding KDM6A, KMT2D and EP300 are highly mutated in human cancers." (PMID 37410700, 2023). "Loss-of-function (LOF) mutations of the lysine acetyltransferase CREBBP are very early events in FL pathogenesis, already detectable in cancer precursor cells, while LOF mutations of the lysine transferase KMT2D are the most common epigenetic hits in this disease." (PMID 38022603, 2023). "KMT2D (lysine methyltransferase 2D) is a widely studied gene in the cancer context." (PMID 37756103, 2023). "Recurrent somatic mutations in chromatin remodeling-related genes have been detected with high frequency in human cancers, and three of them, including KMT2D, ARID1A and KMT2C, were the third, fifth and seventh-most commonly mutated cancer genes in a pan-cancer cohort containing around 33,000 cases." (PMID 35681795, 2022). "We and others have previously demonstrated chromatin-associated mechanisms by which PI3K supports cancer development and antagonizes ER signaling through the modulation of the H3K4 methylation axis, inhibition of KDM5A promoter H3K4 demethylation and KMT2D/MLL4-directed enhancer H3K4 methylation." (PMID 36970726, 2022). "Genes of interest from the selected cancer‐related gene set, restricted to gene mutations occurring in >3 patients, revealed mutations in several genes previously reported in FL (e.g., CREBBP, BCL2, KMT2D)." (PMID 34791836, 2022). "Histone lysine methyltransferase 2D (KMT2D) is widely present in many cancers." (PMID 34758724, 2021). "It has been reported that KMT2D activates pro-tumorigenic enhancers in different types of cancer." (PMID 34194626, 2021). "Notably, KMT2D (also called MLL4, ALR, and MLL2) is the biggest H3K4 methyltransferase and is frequently mutated in many different types of cancer." (PMID 34194626, 2021). "Notably, the histone lysine methyltransferase KMT2D (a COMPASS/ Set1 family member; also known as MLL4, ALR, and MLL2) is among the most frequently mutated genes in many different types of cancer." (PMID 34194626, 2021). "For our investigation of cancer survival-related mechanisms, we first analyzed the protein structure of KMT2D, which consists of many known components, such as plant homeotic domains (PHDs), high mobility group I (HMG I), FY-rich N-terminal (FYRN), FY-rich C-terminal (FYRC), and SET domain." (PMID 34758724, 2021).
cancer (continued). "In the unclassified subgroup, apart from previously reported mutations in epigenetic regulators in multiple cancers, including KMT2C, KMT2D, KMT2B, PRDM2, NCOR2, KAT6B, and EP300, in this cohort, we also found new recurrent mutations in epigenetic regulators, including CREBBP and PRDM16." (PMID 30950204, 2019). "Up to now, there are no available data regarding KMT2D mutation status in patients with KS that develop cancer." (PMID 26341229, 2015). "For example, it is conceivable that targeting KMT2D may serve as part of a combinatory treatment regimen, provided that a cancer-specific delivery is possible." (PMID 24240169, 2013). "Also in cancer the role of KMT2D mediated DNA methylation has received increased attention." (PMID 35856126, 2023). "Cancer genome sequencing efforts reveal that in addition to mutations in growth-promoting signaling pathways such as in EGFR and KRAS, chromatin-modifying enzymes and epigenetic regulators such as KMT2D, ARID1A, and TET2 are also frequent targets of genetic alterations." (PMID 34236315, 2021). "This study delineates the phosphoregulatory network of KMT2D, positioning it as a dynamic epigenetic effector modulated by MEK-ERK signaling, with broader implications for cancer and developmental disorders." (PMID 41341998, 2025). "S7) there were many known and candidate “cancer genes” (again, of the Cancer Gene Census from COSMIC), including enhanced expression of NRAS, KMT2D, and CD74." (PMID 41187221, 2025). "KMT2D and GATA3 were uniquely identified in African Americans as cancer drivers reported in TCGA data, whereas PIK3CA, MAP3K1, CDH1, and MUC6 were identified in Caucasians." (PMID 37454130, 2023). "Likely, the downregulation of KMT2D plays an important role in ATLL carcinogenesis, but its controversial effects on different cancer types preclude a definite conclusion regarding its role." (PMID 36841815, 2023). "Seven top upregulated emRNAs and related to ccRCC or/and multiple malignant tumors, including CUL9, ATM, ARID1A, KMT2D, PBRM1, PREX2, and SETD2, were selected as candidate biomarkers for further testing." (PMID 36002886, 2022). "For instance, a recent study revealed that the transcription of CTNNB1 in cancer cells was mediated by MEF2A, which can be occupied by KMT2D." (PMID 35477537, 2022).
cancer (continued). "Through mass spectrometry-based phosphoproteomic data analysis, this study reveals a phosphoregulatory network that positions KMT2D as a dynamically phosphorylated epigenetic effector modulated by MEK–ERK signaling, with broad implications in cancer and developmental disorders." (PMID 41341998, 2025). "Finally, the SL interaction between KMT2D and WRN contributes a new layer of understanding in MSI cancer cell vulnerability and potential strategies for identifying patients sensitive to WRN inhibitors." (PMID 39578878, 2024). "Altogether, these results suggest that KMT2DLOF MSI cancers may respond to ICI treatments, and we thus propose KMT2D as a possible biomarker to further stratify MSI cases for ICI treatment." (PMID 39578878, 2024). "Diminished KMT2D levels lead to increased production and release of activin A, which activates the noncanonical p38 MAPK-dependent pathway and drives the epithelial–mesenchymal transition in cancer cells to promote invasiveness." (PMID 38791111, 2024). "Interestingly, the distributions of several known cancer driver genes exhibit significant differences between cancer and normal tissues, such as FAT4, KMT2C, KMT2D, KRAS, PIK3CA, and PTEN." (PMID 39541191, 2024). "In this regard, MLL2/KMT2D and MLL3/KMT2C complexes are required to maintain H3K4me1 levels in enhancers, thereby modulating enhancer activities during development and in cancer." (PMID 36968588, 2023). "Furthermore, the results of the immunohistochemistry analysis verified that the expression of cancer stem cell markers, including CD133 and β-catenin, was decreased in SCC4-derived xenografts when KMT2D was knocked down." (PMID 35477537, 2022). "In addition, immunoblotting assays of cancer stem cell markers, including CD133, OCT4, and ALDH1A1, showed a decrease as KMT2D was knocked down." (PMID 35477537, 2022). "Furthermore, the results of the immunofluorescence assays in PDOs demonstrated that the expression of cancer stem cell markers, such as CD133 and β-catenin, was decreased when cells were transfected with Sh-KMT2D." (PMID 35477537, 2022). "No hereditary cancer predisposition linked to the germline mutations K1992T, G2023R, and L2492R in ATM as well as R466C, R5229H, and S5357T in KMT2D were observed." (PMID 35347810, 2022). "According to existing studies, it is found that SLC2A3 has a high affinity for glucose, which can ensure the effective uptake of glucose by cells, and the low expression of KMT2D significantly affects the effect of SLC2A3, thereby inhibiting cancer cells’ uptake and utilization of glucose." (PMID 35281840, 2022). "Furthermore KMT2D can catalyze H3K4 monomethylation by stabilizing the WDR5 protein and enhancing the interactions between components within the KMT2D–enzyme complex in an LLPS-dependent manner, thus promoting cancer progression." (PMID 34758724, 2021). "Furthermore, mutations were detected in genes that are known for their involvement in other cancer types, such as TERT, KMT2D, PIK3CA, AKT1, CTNNB1 and NR1D1." (PMID 32455687, 2020).
cancer (continued). "Indeed, in recent years, several other studies have been demonstrating that MLL2/KMT2D and MLL3/KMT2C genes are involved in a multitude of cancers." (PMID 29483845, 2018). "Moreover, differences in enhancers’ status defined by H3K4me1 profile, which is regulated by MLL2/KMT2D and MLL3/KMT2C, can be found between normal and cancer cells." (PMID 29483845, 2018). "KMT2D is frequently mutated in human cancers, including SCC from various organ origins, but it is not clear whether p63-KMT2D interaction occurs in cancer cells, or whether this might be the case for other histone lysine methyltransferase members." (PMID 32447427, 2020). "While molecular genetic testing (OncoKids Cancer Panel) showed no established variants of clinical significance, it detected variants of unknown significance detected in APC, KMT2D, and MSH6." (PMID 31702654, 2019). "Molecular genetic testing using OncoKids Cancer Pane revealed no established variants of clinical significance, but some variants of unknown significance including APC, KMT2D, and MSH6 were found." (PMID 31702654, 2019). "Our study supports that KMT2D has distinct roles in neoplastic cells, as opposed to normal cells, and that inhibiting KMT2D may be a viable strategy for cancer therapeutics." (PMID 24240169, 2013). "Given that ARID1A sustains cell proliferation in response to DNA damage and cancer cells lacking ARID1A are potentially vulnerable to cisplatin, we next tried to unravel potential clinical significance of KMT2D in management of HCC." (PMID 39564571, 2024). "Regardless of the potential ways to improve the mathematical analysis of this data, there is a clear relationship between KMT2D and KDM6A that did not happen by chance and extends beyond the scope of altered chromatin modification in cancer and into those of known developmental disorder KS." (PMID 35073341, 2022).
prostate (6 papers, 2021 to 2025). "In the aspect of somatic mutation frequency, patients in the high‐level cluster had a higher frequency of somatic mutations in KMT2D, which has been reported to sustain prostate carcinogenesis and metastasis." (PMID 34128342, 2021).
infection (5 papers, 2021 to 2023). The state of being infected such as from the introduction of a foreign agent such as serum, vaccine, antigenic substance or organism. "Combining these findings, our data suggests that KMT2D dysfunction causes sensorineural hearing loss compounded with external factors, such as infection." (PMID 38254937, 2023). "Moreover, as predicted from the screen data, ZBTB7A and KMT2D were important for infection with HIV-1 envelope but had a minimal effect on infection with the HIV-1 pseudotyped with VSV-G." (PMID 36744886, 2023). "To determine whether the defects observed in naïve CD8+ T cells from Kmt2d KO mice in vitro occur in vivo, we applied the Listeria monocytogenes-OVA (rLM-OVA) infection model in Kmt2d KO and Kmt2d WT mice." (PMID 36741385, 2022). "We next asked whether KDM6A/KMT2D/p300 axis is required for infection of other coronaviruses." (PMID 37410700, 2023).
neurodevelopmental disorder (4 papers, 2019 to 2025). A behavioral and cognitive disorder with onset during the developmental period that involves impaired or aberrant development of intellectual, motor, or social functions. "Other highly enriched genes for nsDNV—KMT2D (OMIM 147920), KMT2A (OMIM 605130), NSD1 (OMIM 117550), TAB2 (OMIM 614980), and ADNP (OMIM 615873)—have been previously associated with different types of neurodevelopmental disorders with co-occurrence of CHD." (PMID 34324492, 2021).